EZH2 (enhancer of zeste 2 polycomb repressive complex 2 subunit)
Diseases named in the same sentence as EZH2 in open-access papers (continued):
Sharing a sentence is not in itself a finding about the gene and the disease.
tumor (continued). "Studies from other tumor models have demonstrated that EZH2 inhibits expression of PDL1 and the MHC class 1 antigen processing pathway." (PMID 36910138, 2023). "To further reduce the number of candidate regulators, we first focused on genes function as a tumor suppressor role among those downregulated by EZH2." (PMID 36622753, 2023). "Given the increased metastatic potential of Ezh2 null tumor cells, we tested if FOXP2 overexpression changed migratory capability by transwell migration assays." (PMID 36670102, 2023). "For a more comprehensive understanding of the tumor-suppressive function of EZH2, we kindly direct readers to Section “EZH2 (KMT6)”." (PMID 38036730, 2023). "Specifically, EZH2 expression was increased in GC tissues, and the higher the expression level, the higher the malignant degree of the tumor and the worse the prognosis." (PMID 36672374, 2023). "Strikingly, both NK or CD8+ T cell depletion mitigated long-term survival and prevented complete tumor responses induced following T/P treatment of animals with EZH2 suppressed KPC1 and KPC2 PDAC tumors." (PMID 37142692, 2023). "In murine models of either CRC or Lewis lung cancer (LLC), blocking EZH2 with GSK126 in immunocompetent mice impaired anti-tumor immunity by boosting systemic MDSCs expansion and accumulation in TME." (PMID 36900330, 2023). "Tumor volume and weight of mice treated with sh-EZH2 + oe-NC were observed to be reduced while they were increased in the presence of sh-EZH2 + oe-PFKFB4." (PMID 37179372, 2023). "As a key tumor suppressor of P21, EZH2 can silence the transcription of P21 by combining with its promoter region, leading to the proliferation of GC cells." (PMID 36545914, 2023). "Given that EZH2 is considered a major tumor marker and an effective therapeutic target for OC, herein, we evaluated the impact of two EZH2 inhibitors (GSK343 and EPZ6438) on CTO proliferation and polyploidization." (PMID 37634008, 2023). "The in vitro and in vivo models demonstrated that EPIC induced tumor immune evasion and resistance to immunotherapy by epigenetically suppressing the tumor cell antigen presentation through EZH2 interaction." (PMID 38068923, 2023). "In triple-negative breast cancer, EZH2 acts as a transcriptional activator of the NF-KB subunit RelB to drive self-renewal and promote tumor initiation." (PMID 37664059, 2023). "Undoubtedly, EZH2 has multiple functions in tumor biology and new mechanisms remain to be discovered." (PMID 36629984, 2023). "Taken together, knockdown of EZH2 inhibited tumor growth in vivo by mediating the FBXL7/PFKFB4 axis." (PMID 37179372, 2023). "As its major catalytic subunit, EZH2 exerts epigenetic repression by catalyzing methylation of lysine 27 of histone H3, resulting in inactivation of some tumor-suppressor genes or activation of oncogenes." (PMID 37268997, 2023). "It follows that EZH2 directly interacts physically with several transcription factors in tumor cells and exerts histone methyltransferase activity independently of the PcG family." (PMID 36672374, 2023). "The elevated EZH2 activity in the tumor cell with the alteration of SWI and SNF subunits suppresses the function of Th1-type chemokines and IFN-g-responsive genes." (PMID 37371564, 2023). "Many studies have shown that EZH2 is related to the malignant biological characteristics of tumors, such as tumor malignant proliferation, cycle, apoptosis and migration." (PMID 37198697, 2023). "Immunohistochemical (IHC) staining showed that Ezh2 null tumor cells had significantly lower EZH2 expression than Ezh2 WT, and that Ezh2 heterozygous cells had intermediate levels of EZH2 expression." (PMID 36670102, 2023). "Recent evidence suggests that enhancer of zeste homolog 2 (EZH2) is substantially expressed in tumor cells exposed to hypoxia." (PMID 37179372, 2023).
tumor (continued). "In contrast, knockdown of EZH2 resulted in DNA demethylation and subsequent upregulation of miR-124-3p levels, which inhibited the expression of its target CCL2 in tumor cells, causing arrest of M2 polarization of TAMs." (PMID 37208442, 2023). "Based on functional pathway enrichment analysis, it was found that EZH2 participated in tumor development and progression by modulating multiple signaling pathways and functions, such as negative regulation of gene expression and epigenetics and cell cycle." (PMID 36545914, 2023). "Our results identified EZH2 as the most characteristic feature of CSCs, suggesting that EZH2 inhibitors are a potential treatment option for tumor stem cells in OS." (PMID 36588108, 2023). "It has been reported that miR-26b-5p, functioning as a tumor suppressor, regulates the carcinogenesis and oxaliplatin resistance of GC by targeting EZH2." (PMID 36737782, 2023). "On the one hand, inhibition of EZH2 can directly lead to an increased apoptosis of MM cells and exert anti-tumor effects." (PMID 37239949, 2023). "The lncRNA PAR5 has been recently characterized by our group as a tumor suppressor lncRNA acting through the interaction and inhibition of the Enhancer Of Zeste 2 (EZH2) protein in anaplastic thyroid cancer." (PMID 37238229, 2023). "The EZH2 levels in 20 of 24 tumor tissue samples (83.3%) were increased by ≥ 2-fold in contrast to in normal adjacent tissues." (PMID 37689710, 2023). "Restricting glucose uptake of T cells from TME inhibited EZH2 expression, which indirectly inhibited the Notch signaling through suppressing the two Notch repressors, Numb and Fbxw7, leading to dampening anti-tumor activity of T cells." (PMID 37131214, 2023). "All but two of the carcinomas with ≥10% POU2F3 hotspot staining also had EZH2 staining in ≥80% of tumor cells." (PMID 37190202, 2023). "Although poorly studied in MPM, EZH2-dependent epigenetic reprograming can modulate tumor cell immunogenicity and TME composition, and it can directly regulate immune cell differentiation and functional activation." (PMID 36900330, 2023). "This dual role highlights the need for further in vivo research on NK cell tumor cytotoxicity following EZH2 inhibition." (PMID 37090711, 2023). "The tumor PTPN11mut/SETBP1mut/TP53hom cell clone exhibited loss of heterozygosity for the BRAF and EZH2 genes, which was consistent with FISH data." (PMID 37684264, 2023). "A combination of EZH2 inhibitors promotes the epigenetic reprogramming of tumor cells and reverses the process of resistance to immunomodulators." (PMID 37239949, 2023). "Among 31 single HMTs with expression in all samples, 19 showed a marked up-regulation in RB1-mutant tumours, with particularly notable up-regulation of EZH2, DOT1L, and NSD2, while only 5 displayed a clear down-regulation." (PMID 37883365, 2023). "Among the genes with the most significant changes, we were more interested in EZH2, a well‐known tumor gene that drives the malignant progression of various tumors." (PMID 36479622, 2023). "Tazemetostat, an FDA-approved EZH2-inhibitor, seems to harbor promising anti-cancer properties in various tumor types." (PMID 36900361, 2023). "Incidentally, both oncogenic and tumor suppressive functions have been reported for the H3K27me3 writer, EZH2." (PMID 37569534, 2023). "We have previously shown that when ERβ is expressed, it is able to switch these oncogenic properties of EZH2 for tumor suppressive purposes." (PMID 36926316, 2023). "Accordingly, in hepatic cancer, the inhibition of EZH2 in tumor cells enhanced NK recruitment via CXCL10, and it enhanced their activation through the expression of NKG2D ligands." (PMID 36900330, 2023). "EZH2 plays a potential oncogenic role, correlating with high proliferative index and tumor grade in OC." (PMID 37634008, 2023).
tumor (continued). "Many studies have shown that EZH2 can activate the transcription of some lncRNAs in tumor cells and plays a key role in the occurrence, progression, proliferation, and apoptosis of tumors." (PMID 37988356, 2023). "After further injection of exosomes, expression of EZH2, p‐PI3K, p‐AKT and Ki‐67 was decreased, while expression of PTEN and miR‐30b‐5p was elevated in tumour tissues in the presence of oe‐EZH2." (PMID 37698037, 2023). "Of note, EZH2 inhibitors in combination with CAR-T therapy boost the anti-tumor activity of CAR-T in Ewing sarcoma by reducing H3K27me3 mark and inducing the surface expression of GD2, a stemness marker in tumor cells." (PMID 39086678, 2023). "Nonetheless, this study focuses on the immunofunction of EZH2 in the tumor microenvironment and its effect on the cell cycle." (PMID 37069494, 2023). "AMPK phosphorylates Ezh2, a necessary histone methyltransferase, at T311 site, and in turn disrupts the interactions between Ezh2 and Suz12, which leads to the inhibition of tumor growth." (PMID 36677797, 2023). "Here, we uncovered un-appreciated roles for EZH2 heterozygosity and full deficiency in regulating tumor status, whereby Ezh2 heterozygous tumors had lower tumor burden, lower nuclear grade and were less lethal than Ezh2 null tumors." (PMID 36670102, 2023). "Further, we reported the detection of HCMV in GBM tumor biopsies displaying enhanced EZH2, Myc, and Akt expression." (PMID 37147437, 2023). "Among these PKMTs, SETD2, SETD7, and EZH2 are relatively well characterized with dominant tumor-suppressive functions." (PMID 38036730, 2023). "This leads to overexpression of methyltransferase EZH2, which induces the proliferation and migration of tumor cells and contributes to the development of tumor vascularization." (PMID 36834933, 2023). "Further results suggested that EZH2 expression positively correlated to immune checkpoint molecule expression in most tumor types, especially in KIRC and THCA." (PMID 36545914, 2023). "Tumor tissues were found to have significantly higher EZH2 expression than healthy control (tumor vs. control: median EZH2 expression 11.07 (IQR = 1.02) vs. 10.24 (IQR = 1.13); p < 0.0001)." (PMID 37297005, 2023). "Analysis on the tumor tissues of mice using HE staining found obvious inflammatory cell infiltration in mice treated with sh-NC + oe-NC but silencing of EZH2 reduced inflammatory cell infiltration." (PMID 37179372, 2023). "EZH2, an epigenetic regulator, overexpressed in various tumours, can help cells acquire invasive properties." (PMID 37664042, 2023). "Both pharmacologic and genetic inhibition of EZH2 reduce tumor viability in models of H3K27M DMGs and PFAs, suggesting that the tumors rely on residual PRC2 activity." (PMID 36759899, 2023). "During the past decade, EZH2 has been identified as an oncogene in many types of cancers and acts through epigenetic repression of various tumour suppressor genes." (PMID 37689710, 2023). "The results showed that the expression level of EZH2 protein in GC was higher than that in normal gastric tissue, and positively correlated with tumor-node-metastasis (TNM) stage and lymph node metastasis." (PMID 36672374, 2023). "EZH2 is overexpressed in a variety of tumor tissues, and high EZH2 expression is positively correlated with clinicopathological features and poor prognosis of cancers." (PMID 38008711, 2023). "The findings collected from this study supported the promoting effect of hypoxia on the glucose metabolism and tumor growth of NSCLC via regulation of the EZH2/FBXL7/PFKFB4 axis." (PMID 37179372, 2023). "Whereas, EZH2 knockdown can delay the progression of NSCLC in vivo by enhancing anti-tumor immune responses." (PMID 37179372, 2023). "HCMV-positive tumor biopsies displayed mostly an enhanced EZH2 and Akt with a limited Myc expression." (PMID 37634008, 2023).
tumor (continued). "Histological analysis showed positive staining for cytokeratin 19 in both A/N+E2 and A/N+V transfected induced tumours, and histochemical staining further demonstrated the overexpression effects of Ezh2." (PMID 38050190, 2023). "Several studies have demonstrated that FOXM1 cooperates with EZH2 to promote tumor growth, metastasis, and radioresistance." (PMID 37686402, 2023). "Many studies have shown that overexpression of EZH2 in tumor tissues is closely related to tumor malignancy, poor therapeutic effect, and worse survival." (PMID 37543653, 2023). "Metabolic profiles in isogenic cells responded to changes in EZH2 activity showing shifts in key biosynthetic pathways that play a role in tumor survival." (PMID 37511137, 2023). "Consistent with previous in vitro findings, EZH2 promoted xenograft tumour growth, reflected by larger tumour mass and heavier tumour weight." (PMID 38050190, 2023). "Given that EZH2 inhibitors can modulate both anti-tumor and pro-tumor immune cell populations, a better understanding of the effect of EZH2 inhibitors on the MPM immune infiltrate will likely help physicians determine the most effective combination approaches." (PMID 36900330, 2023). "Because of the few normal tissues in the TCGA database, the data from GTEx normal samples were integrated to examine the different expressions of EZH2 between tumor and corresponding paracancerous tissues." (PMID 36545914, 2023). "EZH2 inhibitors have led to tumour suppression in vitro and in vivo, and there are numerous clinical trials in progress." (PMID 38275587, 2023). "Tumor biopsies displayed an enhanced EZH2 and Myc expression in both MGMT promoter methylated and unmethylated tissues, particularly in MGMT promoter unmethylated ones." (PMID 37147437, 2023). "It was identified as a downstream target of Myc oncogene, the latter coordinately regulating EZH2 through transcriptional and post-transcriptional mechanisms during tumor initiation and disease progression." (PMID 37147437, 2023). "Enhancer of zeste homolog 2 (EZH2) is a well-known epigenetic modifier that functions as an oncogene in tumors by promoting the H3K27me3-mediated transcriptional repression of tumor suppressor genes." (PMID 38008711, 2023). "Recent studies have revealed a critical role of EZH2 in proliferation, metastasis, drug resistance and immune regulation of tumor cells." (PMID 36629984, 2023). "EZH2 functions as an epigenetic silencer in tumor-infiltrating Treg cells to inhibit the expression of IL-4 and IFN-γ, while enhancing Foxp3 expression and Treg activation." (PMID 37909018, 2023). "In another study, a lncRNA termed Low expressed in Bladder Cancer Stem cells (lnc-LBCS), which contributes to weak tumorigenesis and enhanced chemosensitivity of bladder CSCs, was shown to recruit EZH2 to exert an unexpected tumor-suppressive role." (PMID 36768150, 2023). "In a cohort of MTCL (n = 50), EZH2 protein expression was compared to healthy lymph node samples (n = 10) and found to be significantly elevated in tumor tissue (tumor vs. control: median EZH2 H-score 85.0 (IQR = 115.0) vs. 30.0 (IQR = 28.0); p = 0.0063)." (PMID 37297005, 2023). "TNBC cells with increased EZH2 expression were more likely to metastasize, whereas inhibition of EZH2 activity reduced tumor spread and metastasis." (PMID 37372340, 2023). "It is reported that SF3B3 is a key regulator of pre-mRNA splicing of EZH2, therefore regulating tumor development." (PMID 36357564, 2023). "Ezh2 heterozygous tumors contained significantly more tumor-infiltrating CD8+ T cells than the other two Ezh2 genotypes, and significantly more monocytes than Ezh2 WT tumors." (PMID 36670102, 2023). "Further exploration led to the identification and validation of CDK1, CCNB1, AURKA, EZH2, and CCNA2, a five-gene signature with high interactions and potentially associated with tumor stemness, hypoxia enhancement, and TME regulation." (PMID 37189841, 2023).
tumor (continued). "Due to few normal tissues in the TCGA database, the mRNA expression data of normal human tissues derived from the GTEx database were integrated to test the differences in mRNA expression of EZH2 between tumor and matched paracancerous tissues." (PMID 36545914, 2023). "EZH2 has different roles in cancer, such as oncogenic, tumor suppressor, cancer cell metastasis, cancer immunity, and metabolism." (PMID 36873948, 2023). "The anticancer efficacy of the different classes of EZH2 inhibitors is dependent on the roles of EZH2 in the tumor." (PMID 37210576, 2023). "Otherwise, it is also possible that each inhibitory chemical has another nonspecific activity affecting other responses to interfere with the tumor-suppressive function of EZH2." (PMID 38036730, 2023). "This study has identified the crucial involvement of EZH2 overexpression in drug resistance and tumor progression and proposes targeting the EZH2/miR-138 axis as a promising therapeutic approach for MM." (PMID 37104009, 2023). "In HCC patients, miR-98 acts as a tumor suppressor by regulating the Wnt/-catenin signaling through direct suppression of EZH2 expression." (PMID 36917438, 2023). "Both LINC00978 and SOX21-AS1 were reported to bind to EZH2 and recruit it to the P21 promoter, leading to enrichment of H3K27me3, transcriptionally inhibiting expression of P21 and promoting tumor growth and metastasis in vivo." (PMID 37268997, 2023). "EZH2 and p16 immunostains were scored semiquantitatively: based on the percentage and intensity of tumor cell staining a binary staining index (“high- or low-expressing”) was calculated." (PMID 38146588, 2023). "A shift from a polycomb repressor to an AR transcriptional coregulator is mediated by the phosphorylation of EZH2 on S21 by Akt, and EZH2 S21 phosphorylation stimulates cellular proliferation and accelerates tumor growth in mouse models." (PMID 38001678, 2023). "The results of our study affirm that a significant association exists between immunohistochemical expression of EZH2 with tumor grade, histological subtype, lymphnode metastasis, and FIGO stage." (PMID 37131568, 2023). "Of the 19 cases with positive EZH2 expression, more than 50% of tumor cells were positive in 12 (25%) samples." (PMID 37353806, 2023). "EZH2 inhibitors restore the secretion of Th1-type chemokines, increase CTLs-tumor infiltration, inhibit tumor progression, and they can improve the efficacy of anti-PD-L1 agents." (PMID 37427115, 2023). "EZH2 is also overexpressed in fusion positive RMS (FPRMS) tumours compared to normal muscle tissue and EZH2 depletion resulted in apoptosis in FPRMS cell models." (PMID 37858275, 2023). "Whereas T/P treatment in the control shRen setting or EZH2 knockdown alone led to some reduction in tumor growth, T/P treatment in the context of EZH2 knockdown produced significant tumor control, with many tumors regressing after just two-week treatment." (PMID 37142692, 2023). "In conclusion, some inhibitors targeting EZH2 have achieved some success, but most anti-tumor studies of EZH2 inhibitors are still in the preliminary stages." (PMID 36672374, 2023). "The inhibition of EZH2/PRC2 enzymatic activity effectively blocks tumor cell growth, metastasis, and angiogenesis of tumor tissue." (PMID 37760442, 2023). "EZH2 has been involved in transcriptional repression, mainly targeting tumor-suppressor genes and thus promoting tumorigenesis." (PMID 37179372, 2023). "For erasing the H3K27me3 mark out of gene promoters, some methods have been used, such as directly or indirectly inhibiting EZH2, incorporating H3K27me3-recognizing synthetic TFs, applying natural anti-tumor agents, or combining with known anti-tumor agents." (PMID 36188615, 2022). "High expression of the EZH2 in HCC accompanies tumor progression and the immunosuppressive microenvironment." (PMID 36275676, 2022). "In CRC, LSD1 and EZH2 interact to accelerate tumor progression and the suppression of either gene can modulate cell proliferation." (PMID 35577773, 2022).